ENSG00000200422
Synonyms: LOC124905267
Gene: Small nucleolar RNA gene on chromosome X (87,146,733 to 87,146,804, forward strand). Ensembl gene ENSG00000200422.
Gene Ontology:
Biological process: RNA processing
Cellular component: nucleolus
Homologues: Orthologues: rat Snord45l1 (71% identical). Paralogues in human: SNORD45B (93% identical), SNORD45A (79% identical), SNORD45C (78% identical).